MMP2 (matrix metallopeptidase 2)
Diseases named in the same sentence as MMP2 in open-access papers (continued):
Sharing a sentence is not in itself a finding about the gene and the disease.
lung carcinoma (397 papers, 2003 to 2026). "Several studies demonstrated that MMP-2 overexpression is associated with increased lung cancer invasiveness and poorer patient survival." (PMID 41155277, 2025). "In this study, we aim to investigate the abundance of SP in lung cancer tissues and its association with MMP-9 and MMP-2 expression, as well as its impact on survival outcomes in lung cancer patients." (PMID 40321254, 2025). "The dysregulation of MMP-2 has been widely associated with the aggressive nature of various malignancies, including lung cancer." (PMID 41155277, 2025). "For example, in cancer, the overexpression of Mmp2 due to specific polymorphisms promotes tumor invasion and metastasis, particularly in breast and lung cancer." (PMID 39769454, 2024). "This polysaccharide was able to significantly inhibit the migration of lung cancer cells A549 via downregulation of MMP-2 activity—which is associated with cancer metastasis—and affect cell viability at a high concentration." (PMID 35621924, 2022). "Berberine treatment suppressed the mRNA expression of extracellular matrix–degrading proteinases MMP2 and urokinase-plasminogen activator (u-PA), which are closely associated with the invasive and metastatic potential of lung cancer cells." (PMID 36359829, 2022). "Tenascin-C is also proteolytically cleaved by MMP-2 and cathepsin B, and degradation was associated with higher recurrence and a worse prognosis for the patients with lung cancer." (PMID 35008401, 2022). "It has been documented that MMP2 is highly expressed in lung cancer and closely associated with a poor prognosis of patients." (PMID 35441564, 2022). "Progression of different types of cancer including lung cancer has been reported to be associated with overexpression of both MMP2 and MMP9 and correlates with metastasis and poor prognosis." (PMID 34209215, 2021). "In lung cancer patients, MnSOD-positive tumors were related to higher MMP-2 expression and caused tumorigenesis, including proliferation and fibrosis progression." (PMID 34578952, 2021). "MMP2/9, belonging to the MMPs family, has been shown to be associated with poor prognosis and metastasis in lung cancer." (PMID 31855281, 2020). "Lung cancer tissue microarray analysis showed gradual and correlated increases in MMP2 and lnc‐MMP2‐2 expression associated with lung cancer progression from normal lung tissue to primary lung cancer tissue to metastatic lung cancer." (PMID 30256540, 2018). "Taken together, our results demonstrate that activation of ERβ in lung cancer cells promotes tumor metastasis through increasing expression of invasiveness-associated MMP-2." (PMID 28915603, 2017). "In this study, we showed that LIN28A expression was associated with MMP2/9 expression in A549 lung carcinoma cells; LIN28A silencing decreased MMP2/9 levels and metastasis." (PMID 28587210, 2017). "The diagnostic value of BALF MMP-2 for lung cancer was evaluated by Receiver operating characteristic (ROC) curves analysis." (PMID 29113325, 2017). "Single nucleotide polymorphisms (SNP) in MMP-9 are significant predictors for lung cancer development and MMP-2 polymorphisms predict overall survival." (PMID 28915603, 2017). "Overproduction of MMPs, especially MMP-2 and -9 has been associated with a more aggressive behavior of lung cancer and mesothelioma." (PMID 23563849, 2013). "In conclusion, our findings show a relationship between the MMP9 variant genotype and protection against the development of lung cancer and that the MMP2 variant genotype modifies the survival time in NSCLC patients." (PMID 22455335, 2012). "To date, a large number of studies have investigated the relationship between genetic variants in the MMP2, 3 and 9 genes and lung cancer risk." (PMID 22455335, 2012). "In the present study, it was investigated the effect of fucoidan on migration, invasion and MMP-2 expression of A549 human lung cancer cells and its underlying anti-metastatic mechanisms of action." (PMID 23226337, 2012).
lung carcinoma (continued). "To date, a large number of studies have investigated the relationship between variants in the MMP2, 3 and 9 genes and cancer susceptibility or metastasis, including lung cancer." (PMID 22455335, 2012). "In lung cancer, its reduced expression is significantly associated with poor prognosis, and restoring its expression can inhibit proliferation and expression of invasion-related key molecules (such as MMP2, MMP9, cyclin D1) and block clonogenic formation." (PMID 41007433, 2025). "Notably, the role of MMP-9 and MMP-2 in the development of brain metastases is of particular interest, given that BM is a leading cause of death in lung cancer patients." (PMID 40321254, 2025). "The findings suggested that MMP2 could be used as a diagnostic and prognostic indicator of lung cancer." (PMID 33115469, 2020). "In our study, we found that MMP2 was highly expressed in poorly differentiated lung cancer tissues, indicating that MMP2 may be associated with the malignant degree of lung cancer." (PMID 33115469, 2020). "To determine whether the downregulation of MMP2/9 caused by loss of LIN28A influenced lung cancer cell metastasis, we carried out migration and invasion assays in A549 cells transfected with LIN28A siRNA." (PMID 28587210, 2017). "Moreover, Studies on both surgical biopsies and on lung cancer cells revealed that the expression level of ERβ and matrix-metalloproteinase-2 (MMP-2) were associated." (PMID 28915603, 2017). "We examined the association between polymorphisms in the MMP2, 3 and 9 genes and lung cancer risk." (PMID 22455335, 2012). "At this point, it could be expected that individuals who smoke and carry the MMP-2-735CC or -1306CC genotype, or the C-735-C-1306 haplotype, are more susceptible to develop lung cancer than those who smoke and carry either the -735TT or -1306TT genotype, or the T-735-T-1306 haplotype." (PMID 37445754, 2023). "Therefore, the motility suppression of lung cancer cells by Smp24 may be associated with its changes of mRNA levels of MMP-2/-9 and TIMP-1/-2 plus F-actin reorganization." (PMID 35878176, 2022). "Tumor-derived exosomes derived from lung cancer cells promote the invasion and migration of lung cancer cells by regulating the expression levels of specific genes, including those encoding the matrix metalloproteinases MMP-2, MMP-9, PTEN, E-cadherin, and ROCK1." (PMID 34511114, 2021). "In addition, the expression of C-MYC, Cyclin D1, Bcl-2, Bcl-xL, COX-2, TWIST1, and MMP2, which are associated with NF-κB signaling, was analyzed to better understand the NF-κB pathways involved in inhibiting lung cancers and was obviously decreased by 160 μM EGCG." (PMID 31777584, 2019). "The observed inverse connection between hsa-miR-125b-5p and MMP-2 suggests that this microRNA is critical in modulating MMP-2-mediated processes in lung cancer progression." (PMID 41155277, 2025). "Overall, these findings provide strong evidence that p38-MAPK activation mediates the suppression of hsa-miR-125b-5p while promoting MMP-2 expression in response to S100A4-RAGE signaling in human lung cancer cells." (PMID 41155277, 2025). "This study determined a novel regulatory mechanism by which hsa-miR-125b-5p modulates MMP-2 expression via RAGE-p38MAPK-NF-κB signaling in lung cancer cells." (PMID 41155277, 2025). "Dysregulated microRNA-mediated control of matrix metalloproteinase-2 (MMP-2) plays a pivotal role in lung cancer (LC) progression, though the inflammatory signaling mechanisms governing its regulation remain poorly understood." (PMID 41155277, 2025). "Taken together, these results provide consistent evidence across different experimental conditions that p38-MAPK and NF-κB signaling are the principal regulators of the miR-125b-5p/MMP-2 axis in SHP-77 lung cancer cells." (PMID 41155277, 2025).
lung carcinoma (continued). "In this work, we investigate the interaction between hsa-miR-125b-5p and MMP-2 in lung cancer cells A549 and SHP-77, with a particular emphasis on the effect of RAGE activation via S100A4." (PMID 41155277, 2025). "SP DNA levels were assessed using droplet digital PCR, and MMP-9 and MMP-2 protein expression were evaluated by immunohistochemistry in 120 lung cancer samples." (PMID 40321254, 2025). "Increased expression of MMP-2 in response to HMGB1 has been previously documented in lung cancer cells, and this expression was significantly reduced by NF-κB inhibition." (PMID 40277915, 2025). "In this study, we provide new insights into the regulatory role of hsa-miR-125b-5p in controlling the expression of MMP-2 through the RAGE-p38MAPK-p65/p50NF-κB axis in human lung cancer cells." (PMID 41155277, 2025). "Matrix metalloproteinase 2/9 (MMP2/9) secretion decreases by 65% in lung cancer, collagen deposition increases by 60% in stroke models, and the Treg proportion decreases by 40% and Th17 expansion increases in rheumatoid arthritis (RA) patients." (PMID 41007433, 2025). "ROCKII triggers JNK1/2 phosphorylation which often promotes lung cancer migration and invasion via enhancing MMP-2 and -9." (PMID 41271627, 2025). "Similar findings in lung cancer link increased Skp2 to enhanced metastasis and invasion via upregulation of MMP-2 and MMP-926." (PMID 39744562, 2025). "In lung cancer, which is responsible for the most cancer-related deaths worldwide, quercetin significantly reduced the protein expression of MMP-2 and MMP-9 and increased TIMP-2 expression." (PMID 39335164, 2024). "Using a combination of in vitro and molecular docking analyses, we found that silymarin effectively reducing the lung cancer cells' motility and invasion by modulation of expression of MMP-2 and MMP-9." (PMID 39431222, 2024). "Clinical studies on lung cancer bone metastasis have found that overactivation of MMP2/MMP9 promotes osteolytic metastasis and bone destruction in advanced cancer." (PMID 38571500, 2024). "In conclusion, the expansion and migration of lung cancer cells were inhibited by the pharmacological effect of Cal via E‐cad/TPA/MMP‐2/Annexin V+/PI‐cells signaling axis in a dose‐dependent way." (PMID 38230908, 2024). "The primary objective of this study to investigate the impact of silymarin on the proliferation of lung cancer A549 cells, particularly by examining its impact on the expression and activity of MMP-2 and MMP-9." (PMID 39431222, 2024). "In lung cancer cells, curcumin treatment was able to inhibit cell invasion via upregulation of miR-874, which directly targets matrix metalloproteinase-2 (MMP-2), and miR-98, which suppresses MMP-2 and MMP-9 pathways by targeting LIN28A." (PMID 38201989, 2024). "MMP-2 can induce the release of transforming growth factor-beta (TGFβ) and the cleavage of interleukin-1β, which are both related to tumor progression in lung cancer." (PMID 39439549, 2024). "Foxp3 was also associated with upregulation of MMP2 and MMP9 in cholangiocarcinoma cells and lung cancer cells, EMT, and metastasis." (PMID 37766222, 2023). "In SAL-treated human lung cancer cells (A549) and human bladder cancer cells (T24), a significant reduction in MMP-2 and MMP-9 activity was found." (PMID 37644107, 2023). "For example, TMEM196 silencing in lung cancer cells and mice resulted in the upregulation of MMP2 and MMP7." (PMID 37367036, 2023). "The role of MMP-2-735C/T and MMP-9 -1562C/T polymorphisms in an increased risk of lung cancer cannot be dismissed." (PMID 37445754, 2023). "Other zymographic studies assessing MMP-2 activity in lung cancer tissue samples compared to normal tissue showed higher lytic activity of cancer." (PMID 37509417, 2023). "Tlr9 activates inflammatory factors such as il-1 and il-8, increasing immune inhibitory factor il-10 secretion and MMP-2 expression to enhance the invasion and metastasis of lung cancer cells." (PMID 36991462, 2023).
lung carcinoma (continued). "Eugenol treatment was shown to reduce MMP-2 (along with phosphate-Akt) expression in a human lung cancer cell line, inhibiting cell viability and impairing cell motility and invasion." (PMID 36770859, 2023). "The reported results of the MMP-2-735C/T and MMP-9-1562C/T polymorphisms and their role in lung cancer risk are frequently conflicting." (PMID 37445754, 2023). "The comparison of lung cancer subtypes in the prevalence of MMP-2-735C/T and MMP-9-1562C/T genotypes complemented our research." (PMID 37445754, 2023). "RPRIN showed tumor‐targeting and MMP2‐stimulated properties, enhancing the cellular uptake of miR‐148a‐3p in lung cancer cells." (PMID 37521428, 2023). "The engagement of TLRs induced NF-κB activation via the TRAF6-TAK1 signaling axis and increases in the production of IL-6, CCL2, CCL20, vascular endothelial growth factor (VEGF), and MMP2, thereby enhancing lung cancer migration and invasion." (PMID 37287005, 2023). "In a similar manner, eugenol treatment was shown to reduce MMP-2 (along with phosphate-Akt) expression in a human lung cancer cell line, inhibiting cell viability and impairing cell motility and infiltration." (PMID 36770859, 2023). "The engagement of TLR3/4 was reported to induce increases in the production of IL-6, CCL2, CCL20, VEGF, and MMP2 through NF-κB activation, thereby enhancing lung cancer migration and invasion." (PMID 37287005, 2023). "MMP-2 is a major gelatinase which can enzymatically degrade gelatin, and is involved in invasion of lung cancer cells." (PMID 36774778, 2023). "In our study, the MMP-2-735C/T genotype frequencies were found to be CC 74.1%, CT 23.2%, and TT 0.9% in the lung cancer patients group, and CC 77.0%, CT 18.0%, and TT 5.0% in the control group, respectively." (PMID 37445754, 2023). "In this study, we evaluated the effect of two polymorphisms in the promoter regions of two human gelatinases, i.e., MMP-2 and MMP-9, on the risk of lung cancer development." (PMID 37445754, 2023). "The PI3K/AKT/mTOR pathway plays an important role in lung cancer cell migration and invasion, specifically in the regulation of MMP2 and MMP9." (PMID 37111758, 2023). "REMAIN was able to effectively transduce miRNA into lung cancer cells and release them via MMP2 responsiveness." (PMID 36171576, 2022). "Some studies reported the association between increased levels of MMP-2, MMP-9 and decreased TIMP-1 in early stage lung cancer." (PMID 36518397, 2022). "It was found that recombinant POSTN enhanced MMP-2 expression in a concentration-dependant manner, which confirms the results obtained earlier on A549 lung cancer cells transfected with POSTN-specific short hairpin (A549.shRNA)." (PMID 35163164, 2022). "In this study, our results showed that rhein have obviously affect in treatment of proliferation and metastasis of chemosensitive and chemoresistant lung cancer cells, and play a role via the Stat3/Snail/MMP2/MMP9 pathway." (PMID 35178453, 2022). "Activation of NK1R promotes the proliferation, colony formation, EMT, MMP2/14 expression, and migration of lung cancer cells." (PMID 35013118, 2022). "From the findings, we can infer that any suppressive effects of coriloxin on the invasive ability of lung cancer cells are exerted independently of MMP-2 and MMP-9 activities." (PMID 35409350, 2022). "This miRNA was also reported to inhibit the growth and aggressiveness of human lung cancer through a FOXM1/cyclin D1/MMP2 axis." (PMID 35129056, 2022). "ATF1 led to the increasing level of MMP2 expression as well as promotion in lung cancer cell migration and invasion." (PMID 35397606, 2022). "In conclusion, we found that rhein inhibits cell proliferation and migration through the Stat3/Snail/MMP2/MMP9 pathway in lung cancer cells." (PMID 35178453, 2022).
lung carcinoma (continued). "The expression of SLIT3 is downregulated in lung tumor tissues and silencing of SLIT3 in lung cancer cells induces epithelial-mesenchymal transition by downregulating E-cadherin and enhancing MMP2 and MMP9 expression." (PMID 35053460, 2022). "For example, TGF-β mediates the regulation of MMP2 expression by exosome lnc-MMP2-2 to promote lung cancer cell invasion and migration." (PMID 35912155, 2022). "MMP-2 plasma concentrations were significantly augmented in the LAC group (all lung cancer patients examined) when compared to healthy subjects (266.7 ± 6.3 ng/ml and 133.2 ± 4.2 ng/ml, respectively; p < 0.0001)." (PMID 36213817, 2022). "After REMAIN was taken up by the lung cancer cells, miR-126-3p is released in the presence of abundant MMP2 in the lung cancer cells, effectively inducing apoptosis of the cancer cell." (PMID 36171576, 2022). "Collectively, these data suggest that CM from CAFs exposed to apoptotic cancer cells inhibits the migration and invasion of lung cancer cells via inhibition of TGF-β1 signaling-related pathways as well as MMP-2 and MMP-12 expression." (PMID 36241874, 2022). "TGF-β promoted the expression of MMP2 by increasing its enhancer activity, thereby regulating the migration and invasion of lung cancer." (PMID 36463205, 2022). "The in vitro cytotoxicity of doxorubicin was studied on two different cell lines, including MMP-2 high-expressing lung cancer A549 cells and MMP-2 low-expressing MCF-7 cells." (PMID 35586209, 2022). "Overexpression of both MMP2 and MMP9 is known to be associated with the progression of different types of cancer including lung cancer and correlates with metastasis and poor prognosis." (PMID 33958632, 2021). "In human A549 lung carcinoma cells, berberine hydrochloride inhibits cell proliferation and promotes cell apoptosis via regulating the MMP-2 and the Bcl-2/Bax signaling pathways." (PMID 35046810, 2021). "Cytoplasmic and stromal MMP2 expression was reported in lung cancer patients and many studies have correlated lung cancer invasion and metastasis with high expression of MMP2 and MMP9112,113." (PMID 33958632, 2021). "TGF-β induced the expression of MMP2 commonly in three lung cancer cells and other MMPs were regulated differentially depends on cell types." (PMID 34253166, 2021). "The polypepeptide (Ac-GPLGIAGQ) MPP substrate was used to target overexpressed MMP2 in lung cancer cells." (PMID 34834387, 2021). "Wei et.al demonstrated that overexpression of BTG2 inhibits the protein expression of cyclin D1, MMP-1, and MMP-2, and inhibit the growth, proliferation, and invasiveness of the A549 human lung cancer cell line." (PMID 34861847, 2021). "Here, we found that knockdown of FOXH1 significantly decreased the expression of mesenchymal markers (Slug, Snail, MMP2, N-cadherin, and Vimentin), while increasing the expression of epithelial marker (E-cadherin) in lung cancer cells." (PMID 34090445, 2021). "On the other hand, the over-expression of PGM5P4-AS1 significantly inhibited the expression of CyclinD1 (0.37±0.05 vs. 0.93±0.09), MMP-2 (0.41±0.07 vs. 1.22±0.17), Bcl-2 (0.30±0.05 vs. 1.05±0.14), and Bcl-xl (0.37±0.06 vs. 0.91±0.11) in lung cancer cells." (PMID 33315502, 2021). "It was demonstrated that TGF-β induced the expression of MMP2 and Galunisertib reversed the changes of MMPs in three kinds of lung cancer cells." (PMID 34253166, 2021). "Berberine downregulates histone deacetylases in lung cancer (A549) cells, resulting in a decrease in the expression of mRNA and protein of the MMP-2 and MMP-9, inhibiting cell migration and invasion." (PMID 35046810, 2021). "Overexpression of MMP2 and MMP9 has been linked to the progression of various types of cancer including lung cancer and correlates with cell invasion, metastasis, and poor prognosis." (PMID 34209215, 2021). "We report the discovery that MEST regulates lung cancer metastasis by activating the VCP/NF-κB/MMP2 signaling pathway." (PMID 34560900, 2021).